RNU6-441P (RNA, U6 small nuclear 441, pseudogene)
Gene: Small nuclear RNA gene on chromosome 10 (82,340,771 to 82,340,876, forward strand). Ensembl gene ENSG00000207275.
Homologues: Orthologues: chimpanzee U6 (100% identical), macaque U6 (96% identical), dog U6 (85% identical), mouse Gm23516 (83% identical), pig U6 (75% identical). Paralogues in human: RNU6-16P (90% identical), RNU6-38P (90% identical), RNU6-20P (89% identical), RNU6-1145P (88% identical), RNU6-1316P (88% identical), RNU6-25P (88% identical), RNU6-29P (88% identical), RNU6-39P (88% identical), RNU6-574P (88% identical), RNU6-820P (88% identical), RNU6-1 (87% identical), RNU6-1323P (87% identical), and 1285 more.